ENSG00000282278 (novel FIP1L1-PDGFRA fusion protein)
Gene: Protein-coding gene on chromosome 4 (53,377,839 to 54,295,272, forward strand). Ensembl gene ENSG00000282278.
Genetic constraint (gnomAD): Loss-of-function variants: 16 observed, 60.61 expected, observed/expected ratio (o/e) 0.26, 90% interval 0.18 to 0.4. Missense variants: 537 observed, 747.99 expected, observed/expected ratio (o/e) 0.72, 90% interval 0.67 to 0.77. Synonymous variants: 245 observed, 265.22 expected, observed/expected ratio (o/e) 0.92, 90% interval 0.83 to 1.03.